PAH (phenylalanine hydroxylase)
Diseases named in the same sentence as PAH in open-access papers (continued):
Sharing a sentence is not in itself a finding about the gene and the disease.
phenylketonuria (continued). "Phenylketonuria (PKU) is a rare autosomal-recessive metabolic disorder in which a deficiency in the hepatic enzyme phenylalanine hydroxylase (PAH) results in complete or partial inability to metabolize phenylalanine (Phe) into tyrosine." (PMID 30268140, 2018). "Affecting 1 in 15,000 people worldwide, phenylketonuria (PKU) most commonly occurs when any two of the known 700+ loss-of-function mutations in the gene for the hepatic enzyme PAH (phenylalanine hydroxylase) are inherited by a patient." (PMID 28520731, 2017). "Phenylketonuria (PKU) is the autosomal recessive deficiency of phenylalanine hydroxylase resulting in the accumulation of phenylalanine (Phe) in blood and in the brain." (PMID 29291362, 2017). "Phenylketonuria (PKU) is an autosomal recessive inborn error of phenylalanine metabolism caused by deficiency in the enzyme phenylalanine hydroxylase that converts phenylalanine into tyrosine." (PMID 29025426, 2017). "In humans, mutations in phenylalanine hydroxylase cause phenylketonuria, the most common metabolic disease." (PMID 28441450, 2017). "Phenylketonuria (PKU) is an autosomal recessive disease caused by deficient activity of phenylalanine hydroxylase." (PMID 27623981, 2017). "Phenylalanine hydroxylase (PAH) gene is the well-known causative gene for classic Phenylketonuria (PKU) (OMIM#261600) disease, with more than 500 reported mutations." (PMID 28706611, 2017). "Through this study, a novel mutation in the PAH gene in an Iranian pedigree with phenylketonuria was introduced." (PMID 28706611, 2017). "Phenylketonuria (PKU) is an autosomal recessive disorder caused by deficiency in hepatic phenylalanine hydroxylase and is usually diagnosed early in life." (PMID 27595068, 2016). "In Phenylketonuria mutations in the phenylalanine hydroxylase gene (OMIM Entry-# 261600) result in elevated phenylalanine, with intellectual disability and seizures being characteristic of the disease." (PMID 26864449, 2016). "Phenylketonuria (PKU) is an inborn error of amino acid metabolism resulting from deficiency of phenylalanine hydroxylase, the key enzyme for phenylalanine metabolism." (PMID 26064996, 2015). "For example, in phenylketonuria, a mutation in the gene for a hepatic enzyme phenylalanine hydroxylase (genetic susceptibility) results in disease only in the presence of a diet consisting of the amino acid phenylalanine (environmental trigger)." (PMID 25786237, 2015). "Phenylketonuria (PKU) is an autosomal recessive disease caused by a deficient activity of Phenylalanine Hydroxylase (PAH), the enzyme which metabolizes Phenylalanine (Phe) to Tyrosine (Tyr)." (PMID 24773629, 2014). "For example, the effect of phenylalanine hydroxylase mutations on the phenotype of phenylketonuria depends on dietary phenylalanine consumption." (PMID 24794218, 2014). "Phenylketonuria is caused by mutations in the gene encoding the hepatic enzyme phenylalanine hydroxylase (PAH), which catalyzes the conversion of phenylalanine (Phe) to tyrosine." (PMID 23940767, 2013). "We describe a rational, stable method for screening and combining assay conditions for the genetic analysis of 42 Phenylketonuria-associated mutations in the phenylalanine hydroxylase gene." (PMID 21445337, 2011). "Phenylketonuria is an inherited metabolic disorder caused by a deficiency of the specific enzyme phenylalanine hydroxylase (PAH)." (PMID 22346620, 2011). "Phenylketonuria (PKU) is an inborn error of the metabolism resulting from a phenylalanine hydroxylase deficiency." (PMID 20478016, 2010). "Here, we report a synthetic mammalian self-regulation system designed to dynamically respond to l-phenylalanine (Phe), an essential amino acid that accumulates to toxic levels in patients with phenylketonuria (PKU) due to mutations in the Phe hydroxylase (PAH) gene, leading to severe neurotoxicity." (PMID 41189055, 2025).
phenylketonuria (continued). "However, the catabolism of phenylalanine to tyrosine is hampered in patients with phenylketonuria due to a deficiency of the phenylalanine hydroxylase (PAH) enzyme, causing an accumulation of phenylalanine in the blood (hyperphenylalaninemia)." (PMID 36768551, 2023). "The PAH gene is specifically expressed in the human liver and is associated with phenylketonuria." (PMID 37869495, 2023). "Phenylketonuria (PKU) is caused by mutations in the phenylalanine hydroxylase (PAH) gene." (PMID 37004080, 2023). "Professor Yanling Yang from Peking University First Hospital provided an example on the conference: a mutation of phenylalanine hydroxylase (PAH) on the 53rd amino acid was first detected in phenylketonuria (PKU) patients; it had long been considered to be pathogenic and treatment was derived." (PMID 35547959, 2022). "Maternal phenylketonuria is a group of congenital malformations that occur in children of mothers with untreated hyperphenylalaninemia or phenylketonuria (an autosomal recessively inherited disorder of phenylalanine metabolism caused by the mutation in the phenylalanine hydroxylase (PAH) gene)." (PMID 35053723, 2022). "Phenylketonuria (PKU) is caused by mutations in the phenylalanine hydroxylase gene." (PMID 35477497, 2022). "Phenylketonuria (PKU) is caused by autosomal recessive variants in phenylalanine hydroxylase (PAH), leading to systemic accumulation of L-phenylalanine (L-Phe) that may reach neurotoxic levels." (PMID 33824313, 2021). "Phenylketonuria is an autosomal recessive inherited error of metabolism resulting from a deficiency in phenylalanine hydroxylase (EC 1.14.16.1), an enzyme that catalyzes the hydroxylation of phenylalanine to tyrosine, the rate-limiting step in phenylalanine catabolism." (PMID 30067850, 2018). "Methylmalonic acidemia, phenylketonuria, and primary carnitine deficiency were the major IEMs and the mutations in PAH, SLC22A5, and MMACHC genes are the leading causes of IEMs resulting in phenylketonuria, primary carnitine deficiency, and methylmalonic acidemia, respectively, in Jining area." (PMID 29731766, 2018). "Phenylketonuria (PKU) is caused by deficiency of the enzyme phenylalanine hydroxylase (PAH)." (PMID 27623981, 2017). "Mutations in Phenylalanine Hydroxylase (PAH) gene cause phenylketonuria." (PMID 26666653, 2015). "A classic example is phenylketonuria, where inactivating mutations in the PAH gene encoding the enzyme phenylalanine hydroxylase lead to severe intellectual disability in the context of a normal diet, whereas a life-long phenylalanine-restricted diet makes possible a relatively healthy life." (PMID 23820649, 2013). "Phenylketonuria (PKU) is an autosomal recessive genetic condition caused by a PAH gene mutation that results in impaired function of the phenylalanine hydroxylase (PAH) pathway." (PMID 41555437, 2026). "Loss-of-function variants in the human phenylalanine hydroxylase (PAH) gene are the most common genetic causal factors for Phenylketonuria (PKU)." (PMID 42093909, 2026). "Phenylketonuria (PKU) is a rare inherited metabolic disorder that is characterised by a deficiency in the enzyme phenylalanine hydroxylase (PAH), which is crucial for the conversion of phenylalanine (Phe) to tyrosine." (PMID 40710538, 2025). "Phenylketonuria (PKU) is an inborn error of metabolism due to the deficiency of the hepatic enzyme phenylalanine hydroxylase (PAH) (MIM #261600)." (PMID 40292461, 2025). "Phenylketonuria (PKU) is an inherited metabolic disease caused by pathogenic variants in the Phenylalanine Hydroxylase (PAH) gene." (PMID 41390423, 2025). "Phenylketonuria (PKU) is an inherited metabolic disorder caused by pathogenic mutations in the phenylalanine hydroxylase (PAH) gene, leading to decreased PAH activity and increased blood levels of phenylalanine (Phe) in the blood." (PMID 40496820, 2025).
phenylketonuria (continued). "Phenylketonuria (PKU) (OMIM #261600) is an inherited metabolic disease (IMD) characterized by a deficiency of phenylalanine hydroxylase (PAH) enzyme (OMIM #612349), highly expressed in the liver." (PMID 40901071, 2025). "Pathogenic variants in the phenylalanine hydroxylase gene can result in phenylalanine (Phe) accumulation leading to phenylketonuria (PKU; OMIM #261600), a metabolic disease diagnosed in newborn screening." (PMID 40565238, 2025). "Phenylketonuria (PKU), the most common amino acid metabolism disorder, results from a complete or partial deficiency in phenylalanine hydroxylase, the enzyme responsible for converting phenylalanine to tyrosine." (PMID 41010535, 2025). "The main type of HPA is phenylketonuria (PKU), which is caused by homozygous (HO) or compound heterozygous (HE) variants in the Phenylalanine hydroxylase (PAH) gene on chromosome 12q23." (PMID 40420248, 2025). "Phenylketonuria (PKU) results from an inborn error of phenylalanine (Phe) metabolism, which is caused by two variants in the phenylalanine hydroxylase PAH- gene." (PMID 40542360, 2025). "Phenylketonuria (PKU) is an inherited metabolic disorder caused by mutations in the PAH gene, leading to deficient activity of phenylalanine hydroxylase." (PMID 40004633, 2025). "Phenylketonuria (PKU) is a rare metabolic disorder caused by deficient phenylalanine hydroxylase, leading to toxic phenylalanine buildup and severe neurodevelopmental consequences if untreated." (PMID 41377231, 2025). "Phenylketonuria (PKU) is an autosomal recessive disorder caused by a deficiency in the enzyme phenylalanine hydroxylase (PAH)." (PMID 40003301, 2025). "Phenylketonuria (PKU) is an aminoacidopathy disorder which results from deficiency of the phenylalanine hydroxylase enzyme and subsequent phenylalanine accumulation, causing brain damage." (PMID 41250200, 2025). "Phenylketonuria (PKU) is a rare inborn error in phenylalanine (Phe) metabolism mostly caused by autosomal recessive mutations in the phenylalanine hydroxylase (PAH) gene." (PMID 40005006, 2025). "Phenylketonuria (PKU) is a metabolic disorder caused by a deficiency of phenylalanine hydroxylase, the enzyme responsible for catalyzing the hydroxylation of phenylalanine to tyrosine." (PMID 40077059, 2025). "Phenylketonuria (PKU) is an autosomal recessive disease caused by pathogenic variants in the gene PAH, which encodes the hepatic enzyme phenylalanine hydroxylase (PAH)." (PMID 40426720, 2025). "Phenylketonuria (PKU) (OMIM 261600) is an autosomal recessive condition due to deficient activity of phenylalanine hydroxylase (PAH)." (PMID 41318575, 2025). "Phenylketonuria (PKU) is the most common amino acid metabolism disorder, caused by mutations in the phenylalanine hydroxylase (PAH) gene." (PMID 39339813, 2024). "Phenylketonuria (PKU) is an autosomal recessive inherited disorder of phenylalanine (Phe) metabolism that results from a deficiency of phenylalanine hydroxylase (PAH)." (PMID 39679062, 2024). "Phenylketonuria (PKU) is the most common amino acid metabolism disorder caused by a deficiency in the enzyme phenylalanine hydroxylase (PAH)." (PMID 39458458, 2024). "Phenylketonuria (PKU) is a genetic disorder characterized by the deficiency of the enzyme phenylalanine hydroxylase." (PMID 39595585, 2024). "Phenylketonuria (PKU) is an inborn error of amino acid metabolism caused by deficient activity of phenylalanine hydroxylase, which catalyzes conversion of phenylalanine (Phe) into tyrosine." (PMID 39512432, 2024). "Phe is related to classic phenylketonuria (PKU), caused by defective activity of phenylalanine hydroxylase that converts phenylalanine to tyrosine, and can affect brain development and function depending on the timing of exposure to elevated levels." (PMID 39450046, 2024). "Phenylketonuria (PKU), a hereditary error of amino acid metabolism, is a disease caused by variants in the phenylalanine hydroxylase (PAH) gene." (PMID 38248068, 2024).
phenylketonuria (continued). "Phenylketonuria (PKU) is an inborn error of metabolism caused by a deficiency in the enzyme phenylalanine hydroxylase (PAH), which is responsible for converting the amino acid phenylalanine (Phe) into tyrosine." (PMID 39339717, 2024). "Phenylketonuria (PKU) is an autosomal recessive metabolic disorder caused by deficiency of the enzyme phenylalanine hydroxylase (PAH), which converts phenylalanine into tyrosine in the liver." (PMID 38662782, 2024). "The c.1222C>T (p.Arg408Trp) phenylalanine hydroxylase (PAH) variant is the most frequent cause of phenylketonuria (PKU), an autosomal recessive disorder characterized by accumulation of blood phenylalanine (Phe) to neurotoxic levels." (PMID 37922902, 2024). "Phenylketonuria (PKU) is an autosomal recessive hereditary metabolic disorder caused by a deficiency in the activity of phenylalanine hydroxylase (PAH; EC 1.14.16.1)." (PMID 38515136, 2024). "Phenylketonuria (PKU) is a rare metabolic disorder caused by mutations in the phenylalanine hydroxylase gene." (PMID 37446577, 2023). "Phenylketonuria (PKU) is an inherited disease of phenylalanine (Phe) metabolism caused by a deficiency of the hepatic enzyme phenylalanine hydroxylase." (PMID 38053931, 2023). "Phenylketonuria (PKU) is caused by mutations in the phenylalanine hydroxylase (PAH) gene and is characterized by altered amino acid metabolism." (PMID 37189584, 2023). "Phenylketonuria (PKU) is an autosomal recessive metabolic disorder due to mutations of the phenylalanine hydroxylase gene (PAH)." (PMID 37308610, 2023). "Phenylketonuria (PKU) results from biallelic pathogenic variants in the phenylalanine hydroxylase (PAH) gene and is identified in medically advanced countries via newborn screening detection of elevated blood phenylalanine (Phe) concentrations." (PMID 37764724, 2023). "Phenylketonuria (PKU) is an autosomal recessive inherited metabolic disorder with a prevalence of 1 in 10,000 births in Europe caused by a deficiency of phenylalanine hydroxylase (PAH)." (PMID 37400895, 2023). "Neurological deficits are commonly reported in late-diagnosed patients with phenylketonuria (PKU), a rare inborn error of metabolism caused by autosomal recessive mutations in the phenylalanine hydroxylase (PAH) gene." (PMID 37081197, 2023). "One of the most well-known genetic metabolic diseases is phenylketonuria (PKU), which results from mutations in the gene encoding phenylalanine hydroxylase (PAH)." (PMID 37445852, 2023). "Phenylketonuria (PKU) is a rare inherited disorder of amino acid metabolism that is caused by pathogenic variants in the phenylalanine hydroxylase (PAH) gene." (PMID 37242212, 2023). "Phenylketonuria (PKU) is a rare autosomal recessive inborn error of phenylalanine (Phe) metabolism caused by the deficient activity of Phe hydroxylase (PAH), which is needed to convert Phe into tyrosine." (PMID 36138662, 2022). "Its consumption should be avoided by individuals with phenylketonuria (PKU), which is a metabolic disorder characterized by a deficiency of the enzyme phenylalanine hydroxylase that catalyzes the hydroxylation of phenylalanine to tyrosine." (PMID 36360040, 2022). "Phenylketonuria (PKU) is a recessively inherited disorder caused by the mutation of the gene coding for phenylalanine hydroxylase (PAH, EC 1.14.16.1), and it results in the inability to catalyze phenylalanine (Phe) into tyrosine." (PMID 35956311, 2022). "Phenylketonuria (PKU) is an inherited metabolic disorder caused by the mutation of the phenylalanine hydroxylase enzyme, which converts phenylalanine (Phe) into tyrosine." (PMID 35565850, 2022). "Phenylketonuria (PKU) (OMIM 261600) is an autosomal recessive disorder caused by a deficiency of phenylalanine hydroxylase (PAH)." (PMID 35327772, 2022). "In phenylketonuria (PKU), mutations of the phenylalanine hydroxylase (PAH) gene decrease the ability of PAH to convert Phe to tyrosine (Tyr)." (PMID 39872976, 2022).
phenylketonuria (continued). "Phenylketonuria (PKU) is an autosomal recessive disorder of protein metabolism that is caused by a deficiency of phenylalanine hydroxylase, the enzyme which metabolizes the amino acid phenylalanine to tyrosine." (PMID 35276935, 2022). "Phenylketonuria (PKU) is an inborn error of metabolism caused by a deficiency of the enzyme phenylalanine hydroxylase." (PMID 35907851, 2022). "Phenylketonuria (PKU) is an autosomal recessive disease caused by deficient activity of human phenylalanine hydroxylase (hPAH), which can lead to neurologic impairments in untreated patients." (PMID 35335706, 2022). "When the activity of phenylalanine hydroxylase is reduced or lost, a large amount of phenylpyruvate is produced, which may cause phenylketonuria affecting brain development to cause mental retardation, brain malformations, convulsions and other neurological symptoms." (PMID 36090056, 2022). "Phenylketonuria (PKU) is a genetic deficiency of phenylalanine hydroxylase (PAH) in liver resulting in blood phenylalanine (Phe) elevation and neurotoxicity." (PMID 34819582, 2021). "Phenylketonuria (PKU) is a rare autosomal recessive disorder caused by deficiency in activity of the hepatic enzyme, phenylalanine hydroxylase (PAH)." (PMID 34094869, 2021). "Phenylketonuria (PKU) is a genetic disease caused by deficient activity of human phenylalanine hydroxylase (hPAH) that, when untreated, can lead to severe psychomotor impairment." (PMID 33808760, 2021). "Phenylketonuria (PKU) is an inborn error of phenylalanine (Phe) metabolism caused by deficiency of the Phe hydroxylase enzyme (PAH; EC 1.14.16.1), which catalyzes the conversion of Phe to tyrosine, with the help of the cofactor tetrahydrobiopterin (BH4)." (PMID 33807079, 2021). "Phenylketonuria (PKU), an inborn error of amino acid metabolism, is caused by phenylalanine hydroxylase deficiency, an enzyme that converts phenylalanine to tyrosine." (PMID 34836232, 2021). "Phenylketonuria (PKU) is an autosomal recessive inherited disease, which is mainly caused by a mutation in the phenylalanine hydroxylase (PAH) gene, including 60% is missense mutations, and other common variants being splice variants and deletions." (PMID 34920737, 2021). "Phenylketonuria (PKU) is an inborn error of metabolism that results from a deficiency in phenylalanine hydroxylase (PAH), the enzyme catalyzing the conversion of phenylalanine to tyrosine." (PMID 34851303, 2021). "Phenylketonuria (PKU) is an inborn error of metabolism caused by variants in the phenylalanine hydroxylase (PAH) gene and it is characterized by excessively high levels of phenylalanine in body fluids." (PMID 34900593, 2021). "Phenylketonuria (PKU) is a rare, genetic disease caused by mutations in the phenylalanine hydroxylase (PAH) gene; as PAH converts phenylalanine (Phe) to tyrosine (Tyr), its lack causes an accumulation of Phe." (PMID 33722205, 2021). "Our studies identified the highest prevalence of phenylketonuria around the world (birth prevalence 1:850 newborns) in one region of the Russian Federation, and it is associated with the spread of a specific mutation (p.R261∗ in the PAH gene) associated with the founder effect." (PMID 34527017, 2021). "Phenylketonuria (PKU) is a metabolic disorder whereby phenylalanine metabolism is deficient due to allelic variations in the gene for phenylalanine hydroxylase (PAH)." (PMID 33493163, 2021). "Phenylketonuria (PKU) is an autosomal recessive inherited disorder characterised by a deficiency in phenylalanine hydroxylase." (PMID 33461585, 2021). "Phenylketonuria (PKU) is an autosomal recessive metabolic disorder caused by the dysfunction of the enzyme phenylalanine hydroxylase (PAH)." (PMID 33260674, 2020). "Phenylketonuria (PKU) is an inborn metabolic disorder caused by a mutation of the gene encoding for the enzyme phenylalanine hydroxylase (PAH), which converts the amino acid phenylalanine into tyrosine and other components." (PMID 32827285, 2020).